USP2 (ubiquitin specific peptidase 2)
Diseases named in the same sentence as USP2 in open-access papers (continued):
Sharing a sentence is not in itself a finding about the gene and the disease.
psoriasis (1 paper, 2016). An autoimmune condition characterized by red, well-delineated plaques with silvery scales that are usually on the extensor surfaces and scalp. "Moreover, we determined the expression of USP2 in quiescent lymphocytes from healthy individuals (n=3), a T-cell cell line from a psoriasis patient (Psor-2), representing activated T-lymphocytes and a panel of CTCL cell lines, MyLa2000 cells, SeAx and Hut-78 cells." (PMID 27351221, 2016).
sarcopenia (1 paper, 2024). Progressive decline in muscle mass due to aging which results in decreased functional capacity of muscles. "Therefore, USP2 might impede sarcopenia through the preservation of PGC1α." (PMID 39596006, 2024).
steatosis (1 paper, 2024). Increased lipid within the cytoplasm of cells. "Conversely, Usp2 depletion caused diminished steatosis and inflammation." (PMID 38993560, 2024). "To confirm the role of USP2 in fructose-induced steatosis and inflammation, we overexpressed the Usp2 gene in primary hepatocytes, and subsequently treated these cells with FFr." (PMID 38993560, 2024). "Hence, we concluded that USP2 regulates steatosis and inflammation depending on the C/EBPα/ 11β-HSD1 pathway." (PMID 38993560, 2024).
triple-negative breast carcinoma (1 paper, 2020). An invasive breast carcinoma which is negative for expression of estrogen receptor (ER), progesterone receptor (PR), and human epidermal growth factor receptor 2 (HER2). "USP2 is a ubiquitin-specific protease found to be capable of promoting metastasis in triple negative breast cancer." (PMID 32751422, 2020).
ulcers (1 paper, 2022). "Accordingly, USP2 expression was downregulated in the tissues of patients with CD with ulcers compared to that in tissues of patients with CD without ulcers." (PMID 36172047, 2022).
cancer (36 papers, 2014 to 2025). A tumor composed of atypical neoplastic, often pleomorphic cells that invade other tissues. "USP2 has been associated with tumorigenesis and high reported expression levels in malignant tumors." (PMID 37628997, 2023). "Since the roles of USP2 are closely associated with pandemic disorders, including cancer and metabolic diseases, clinical and preclinical studies targeting USP2-associated signaling are desirable." (PMID 33530560, 2021). "Although USP2 is a regulator of oncogenic behavior in cancer through regulating protein stability of diverse substrates, USP2-targeted substrates and the underlying mechanisms of cancer cell death remain unclear." (PMID 37628997, 2023). "Beyond the immune response, this work highlights how a specific enzyme, USP2, may regulate its targets in physio-pathological processes for a better understanding of its pathogenic activity in cancers and inflammation." (PMID 25027767, 2014). "This research offers a solid justification for investigating the potential of 6TG as a treatment for cancers where USP2 activity is elevated." (PMID 39048945, 2024). "To identify novel substrates of USP2 on apoptosis in cancer, we surveyed alteration of apoptotic regulatory proteins stemming from ML364 treatment." (PMID 37628997, 2023). "Subsequent wound healing assay suggested that H1299 cells with USP2 shRNAs transfection elevated cancer cell migration and wound healing after 48 h of incubation." (PMID 36567903, 2022). "Other studies also indicated that USP2 augments the cancer cell cycle by interacting with cyclin D1 and reducing its protein degradation by ubiquitination." (PMID 36567903, 2022). "To summarize, we confirmed that USP2 suppressed cancer cell migration and invasion capabilities through ARID2." (PMID 36567903, 2022). "Study results showed that cancer cells transfected with USP2 shRNAs exhibited significantly promoted ARID2 protein degradation compared with a control group." (PMID 36567903, 2022). "Consistent with this notion, we found in the Cancer Cell Line Encyclopedia gene expression database that the expression level of USP2 was much lower in H460 cells than in U2OS or HeLa cells." (PMID 36436562, 2022). "By comparing USP2 with other DUBs, some review articles have summarized the pathological roles of USP2 in specific functional areas, such as cancer promotion, muscle atrophy modification, and sodium channel regulation." (PMID 33530560, 2021). "The augmentation of cell cycle progression is a common feature of cancer cells, and the roles of USP2 in cell cycle regulation have been relatively well-studied." (PMID 33530560, 2021). "Of note, restraint of USP2 function induced growth suppression only in the cancer cells addicted to cyclin D1 expression, whereas there was no major effect on cell growth of normal human fibroblasts." (PMID 34072267, 2021). "For example, a comprehensive gene expression analysis of 18 human cancer types from the Cancer Genome Atlas categorized USP2 under “consistently downregulated genes” in adrenocortical carcinoma, kidney renal clear cell carcinoma, and thymoma." (PMID 33530560, 2021).
cancer (continued). "Despite plenty of studies reporting the roles of USP2 in cancers, little is known about its roles in the heart." (PMID 32963492, 2020). "USP2 and its isoforms have previously been shown to have oncogenic properties and have been extensively investigated by cancer biologists." (PMID 32549302, 2020). "USP2 has been shown to be overexpressed in a variety of cancers, which is involved in promoting cancer cell proliferation, metastasis, and drug resistance." (PMID 32963492, 2020). "Transwell migration assays showed that knocking down USP2 expression suppressed cancer cell migration and conversely, overexpression of USP2 promoted this effect." (PMID 30918246, 2019). "USP2 regulates cell growth or death and involves in the pathogenesis of various diseases, including malignant tumors." (PMID 30319415, 2018). "Our study provides a clear rationale for the clinical evaluation of 6-thioguanine for USP2-upregulated cancers." (PMID 29449607, 2018). "Our findings support earlier results suggesting that 6TG has a broad spectrum of activity, and have implications with respect to the need for direct clinical evaluation of its use against USP2-upregulated cancers." (PMID 29449607, 2018). "Our findings once again revealed the broad spectrum of activity of 6TG and provides biochemical and structural evidence for evaluating the possible application of 6TG on the clinical or combinational treatment against those USP2-upregulated cancers." (PMID 29449607, 2018). "In contrast, lower expression of the downregulated genes (such as SCARA5, MYOM1, NKAPL, PEG3, USP2, SLC5A7 and HMGCLL1) in various cancers is associated with poor clinical outcomes in cancer." (PMID 28427185, 2017). "USP2a is overexpressed in human prostate adenocarcinomas, and upregulation of USP2 prevents cancer cells from apoptosis upon treatment with chemotherapeutic agents." (PMID 27351221, 2016). "USP2 stabilizes cyclin D1 in order to maintain human cancer cell growth; targeting USP2 is therefore an effective approach to induce growth suppression of cancer cells addicted to cyclin D1 expression." (PMID 26097878, 2015). "As an oncogene, USP2 has been suggested as a therapeutic target in cancers." (PMID 40002179, 2025). "Therefore, we identified survivin as a novel substrate of USP2, and found that USP2-depletion-mediated survivin degradation contributed to TRAIL sensitization of cancer cells." (PMID 37628997, 2023). "Multiple studies have reported several molecular targets of USP2 in cancer cells." (PMID 37628997, 2023). "Furthermore, other reports have demonstrated that previously established anti-cancer drugs inhibit USP2 activity." (PMID 33530560, 2021). "Besides, studies have confirmed that USP2 specifically deubiquitinates cyclin D1 through direct interaction, to regulate the growth of cancer cells." (PMID 33314748, 2021). "In addition to cancer cells, USP2 has been also postulated to modulate tumor necrosis factor (TNF) α–induced apoptosis in hepatocytes." (PMID 33530560, 2021). "Several molecular targets of USP2 have been found in cancer cells." (PMID 33530560, 2021). "Inhibiting USP2a with ML364, a small-molecule inhibitor, downregulates β-catenin in cancer cells, suggesting that USP2 might be a therapeutic target to reduce the cancer-promoting protein β-catenin." (PMID 33158118, 2020). "All of these studies suggest that the inhibition of USP2 may be a good therapeutic approach against cancers." (PMID 29449607, 2018). "USP2 and its isoforms are involved in the development of several types of cancer." (PMID 30319415, 2018). "However, few studies have shown that PLP1, MYOM1, NKAPL, and USP2 were consistently downregulated in various cancers." (PMID 28427185, 2017).
cancer (continued). "USP2 has been shown to promote resistance to chemotherapeutic agents in several cancer models." (PMID 27351221, 2016). "In addition to the NF-κB pathway, a huge and increasing number of proteins and pathways seems to be controlled by USP2, which is also deregulated in many cancers." (PMID 25027767, 2014). "The VCP/USP2/FASN axis could emerge as a compelling therapeutic target in cancer treatment." (PMID 39489738, 2024). "Notably, USP2 has also been intensively studied in cancer pathogenesis." (PMID 36567903, 2022). "Subsequent wound healing assay on the H1299 cells transfected with USP2 shRNAs in combination with or without ARID2 overexpression vectors also suggested that the enhancement of cancer cell migration caused by USP2 shRNAs was also diminished with cotransfection of ARDI2 overexpression." (PMID 36567903, 2022). "The most active anticancer pathways in adiponectin-mediated AMPK action include PI3K/AKT, ERK1/2, STAT3, β-catenin, ubiquitin carboxyl-terminal hydrolase 2 (USP2), and B-cell leukemia/lymphoma 2 (BCL-2) in this type of cancer." (PMID 40563460, 2025). "When USP2 was depleted by siRNA, TRAIL accumulated a sub-G1 population and cleaved PARP in various cancer cells." (PMID 37628997, 2023). "Their modulation of ROS enzymes such as ubiquitin-specific protease-2 (USP2) and NADPH Quinone Oxidoreductase 1 (NQO1) gave them selectivity against cancer cells." (PMID 36500400, 2022). "USP2 and ARID2 demonstrated protein-protein interaction and overlapping localization in cancer cell models." (PMID 36567903, 2022). "USP family members play different functions in cancer, and most of them, such as USP1, USP2, USP7, USP14, and USP17, contribute to cancer promotion." (PMID 33619866, 2021). "ML364 has been identified as a potential small molecule inhibitor of USP2 with an IC50 of 1.1 μM, which induces cellular cyclin D1 degradation leading to cell-cycle arrest in HCT116 cancer cell lines and also has a lower affinity to USP8." (PMID 32549302, 2020). "Altogether, our study illustrates that USP2 overexpression in TNBC promotes Twist/Bmi1 expression, CSC expansion, cancer cell migration and tumor development." (PMID 30918246, 2019). "More importantly, we found a number of genes commonly dysregulated in various cancers such as PLP1, MYOM1, NKAPL and USP2 which were investigated in few cancer related studies, and thus represent our novel findings." (PMID 28427185, 2017). "We identified consistently upregulated genes (such as E2F1, EZH2, FOXM1, MYBL2, PLK1, TTK, AURKA/B and BUB1) and consistently downregulated genes (such as SCARA5, MYOM1, NKAPL, PEG3, USP2, SLC5A7 and HMGCLL1) across various cancers." (PMID 28427185, 2017). "Several members of the DUB family are known to contribute to carcinogenesis, including USP1, USP2, USP7 and USP22, while other DUBs are down-regulated in human cancers, including USP10 and BAP1." (PMID 27030989, 2016). "USPs, such as USP1, USP2, USP7, USP9x and USP14, were recently shown to contribute to the development of cancer and are emerging as novel cancer drug targets." (PMID 27780924, 2016). "Like USP2, USP21 was also reported to deubiquitinate RIP1 and the selective USP21 inhibitor compound BAY-805 may have therapeutic potential in cancer." (PMID 37892185, 2023). "Future studies are clearly warranted to examine whether the combination of USP2 inhibitors and PD1-PD-L1 checkpoint blockade is especially effective in the treatment of human cancer patients in clinical trials." (PMID 37024504, 2023).
cancer (continued). "The pharmacological inhibitor (ML364) and siRNA targeting USP2 enhanced TNF-related apoptosis-inducing ligand (TRAIL)-induced cancer cell death, but not normal cells." (PMID 37628997, 2023). "We also detected apparent colocalization of USP2 and ARID2 within cancer cells." (PMID 36567903, 2022). "When EMT biomarkers were detected in H1299 cells with cotransfection of USP2 shRNAs and ARID2 overexpression vectors, we found that in comparison with cancer cells with USP2 shRNAs transfection, the cotransfection demonstrated notably diminished tendency of mesenchymal phenotype transition." (PMID 36567903, 2022). "Patients with higher expression levels of USP2 have better OS prognoses than those with lower expression levels of USP2 in three cancer types (ACC, KIRC, and PAAD), and better DFS prognoses in three cancer types (ACC, KIRC, and THCA) (log-rank test, unadjusted P-value < 0.05)." (PMID 28427185, 2017). "DUBs are critical key players in diverse processes such as (i) spermatogenesis (e.g. USP2, USP8, USP9y, USP14, USP26, Uchl-1, Uchl-3 and CYLD), (ii) cancer biology (e.g. USP7, USP10 and USP11), and (iii) stemness and differentiation (e.g. USP7, USP9x, USP22, USP44 and Psmd14)." (PMID 28659380, 2017). "Furthermore, ML364 treatment and knockdown of USP2 enhanced TRAIL-mediated apoptosis in cancer cells, but not in normal cells." (PMID 37628997, 2023). "This different effect of USP2 in normal and cancer cells suggests that USP2 may be used as a new drug target to block its activity and reduce the proliferation of cancer cells in a safe and non-toxic way." (PMID 34072267, 2021).
tumor (26 papers, 2016 to 2026). "USP2 was associated with enhanced tumor invasiveness via modulation of MMP2 expression." (PMID 36567903, 2022). "USP28 inhibitors, such as FT206 and vismodegib, destabilize oncogenic substrates (e.g., c‐Myc, HIF1α) by blocking USP2's deubiquitinase activity, thereby suppressing tumor growth." (PMID 40855785, 2026). "Studies indicate that USP2 fosters tumor growth and spread through regulating apoptosis, autophagy, and oncoprotein stabilization." (PMID 38993560, 2024). "Of note, a similar proportion of the ML364-treated mice also achieved long-term survival, demonstrating that USP2 inhibition also exerts anti-tumor effects in vivo." (PMID 37024504, 2023). "Remarkably, all the mice of the combination-treated cohort (9 of 9) displayed dramatic tumor regression and long-term survival, indicating that the combination of USP2 inhibition and PD-1/PD-L1 blockade is an especially effective mode of tumor therapy." (PMID 37024504, 2023). "Since the intracellular content of cyclin D1 is a determinant for tumorigenesis in certain types of tumors, cyclin D1 has been used as an index in the exploration of USP2 inhibitors as anti-tumor drugs." (PMID 33530560, 2021). "In particular, since USP2 modulates the stability of critical tumor-associated proteins such as cyclin D1, Mdm2, and FASN, great efforts have been made to establish a USP2-targeting anticancer drug." (PMID 33530560, 2021). "Animal studies indicate that pharmacological inhibition of USP2 suppresses tumor progression and sensitizes tumor responses to chemotherapy in TNBC." (PMID 30918246, 2019). "Animal studies show that the USP2 inhibitor significantly suppresses tumor growth and increases chemotherapy efficacy in TNBC." (PMID 30918246, 2019). "USP2 thus plays a critical role in tumor cells’ survival and therefore represents a therapeutic target." (PMID 29449607, 2018). "Using qPCR, the expression of the three known USP2 isoforms was determined in the material from paraffin-embedded biopsies from plaque/patch and tumor MF." (PMID 27351221, 2016). "USP2 inhibitors have been reported and could be tested for their effects on MB tumorigenesis and tumor cell proliferation." (PMID 40002179, 2025). "Indeed, USP2 inhibition alone partially induces tumor growth suppression but more strikingly, the combination of USP2 inhibition and PD-1/PD-L1 blockade promote vigorous tumor regression and long-term survival of all tumor-bearing mice." (PMID 37024504, 2023). "Importantly, pharmacological inhibition of USP2 suppresses tumor growth and considerately improves chemosensitivity in TNBC." (PMID 30918246, 2019). "Moreover, upregulation of USP2 in tumor cells is significantly correlated with lymph node metastasis status and pN staging." (PMID 30918246, 2019). "Importantly, administration of the USP2 inhibitor ML364 in TNBC xenograft-bearing mice restarted tumor development as a single agent and considerately improves the effectiveness of doxorubicin as a combination agent." (PMID 30918246, 2019).